BRCA1 (BRCA1 DNA repair associated)
Diseases named in the same sentence as BRCA1 in open-access papers (continued):
Sharing a sentence is not in itself a finding about the gene and the disease.
cancer (continued). "Along with targeting the suboptimal HRR pathway that results from non-functional BRCA1/2, the blocking of the BER pathway with PARP inhibitors significantly improves survival rates of cancer patients." (PMID 29459887, 2018). "First, there was a delay in testing and counselling male individuals from BRCA1 families, since BRCA2 men seemed to be at higher cancer risks and there was no clear recommendation to test men." (PMID 29456621, 2018). "We detectedthat the protein and mRNA expression levels of BRCA1 and MAPT in the cancer tissues were significant lower than that in the adjacent non-tumor tissues (p<0.001)." (PMID 29113350, 2017). "This is because, as it is already known, PARPis result active in tumors deficient in the homologous recombination (HR) mechanisms due to alterations in the BRCA1/2 genes, whereas their action is very negligible in non-BRCA mutant cancers." (PMID 27474173, 2016). "The expression of PARP1, BRCA1 and BRCA2 was not correlated with cancer patients' age, TNM Stage, and pathological pattern of cancer." (PMID 25865228, 2015). "In this study, we modeled a scenario where WGS replaced gene-specific testing in 176 BRCA1/2-carriers and 82 non-BRCA patients from our cancer genetics clinics." (PMID 26023681, 2015). "The expression of HNF1A-AS1 in tumor samples was also significantly correlated with one immunohistochemical markers of cancer, RRM1 (p = 0.006), but not with VEGF, C-erbB-2, TS, BRCA1, ERCC1, Ki67, CD56, Syn, or CgA." (PMID 26472090, 2015). "Many cancer sera showed OD values several fold above the cutoff, indicating that autoantibodies response to three TAAs (PARP, BRCA1 and BRCA2) in some cancer patients were quite robust and not just mildly elevated." (PMID 25865228, 2015). "Finally, the finding that the ubiquitin ligase function of the BRCA1: BARD1 is not required for HDR or tumor suppression in the mouse raises the additional question of why missense mutations of BRCA1 that disrupt the BRCA1: BARD1 interaction (e.g., Cys61Gly) lead to cancer in humans and in mice." (PMID 23802008, 2013). "In a phase I trial of the PARP inhibitor olaparib (formerly AZD2281), significant responses were observed only in BRCA1-mutant and BRCA2-mutant cancers, with no responses in tumors wild-type for BRCA." (PMID 23802008, 2013). "BRCA1 tumors are typically estrogen receptor (ER) negative, progesterone receptor (PR) negative and HER2 negative (triple-negative) cancers, while the majority of BRCA2 tumors are ER positive and HER2 negative." (PMID 23704984, 2013). "It has not been established that mastectomy at the time of a cancer diagnosis is the best therapeutic option, as several studies have shown that the BCSS and/or the OS in BRCA1/2 is no different than that of sporadic cancers." (PMID 22295226, 2011). "In conclusion, our study provides further evidence that BRCA1 is not involved in XIST localization and demonstrate that the detection of XIST in a cancer cell is not indicative of the presence of an inactive X chromosome." (PMID 19440381, 2009). "Similar frequencies of MLH1, BRCA1, and FANCF promoter methylation occurred in primary carcinomas without previous chemotherapy, after neoadjuvant chemotherapy, or in recurrent neoplasms." (PMID 19602291, 2009). "While some genes, such as BRCA1 and BRCA2, have long been known to make a significant contribution to the familial aggregation of certain cancers, the more general question has not been definitively answered since most genes have not been extensively evaluated in association studies." (PMID 40073867, 2025).
cancer (continued). "BRCA1 PV carriers were at increased CBC (HR, 3.60 [95% CI, 2.65 to 4.90]), OC (HR, 33.0 [95% CI, 19.1 to 57.1]), colorectal (HR, 2.93 [95% CI, 1.53 to 5.62]), and nonbreast/ovarian (HR, 1.45 [95% CI, 1.05 to 2.01]) cancer risks compared with noncarriers." (PMID 39475295, 2025). "In addition to the LTBP4 constitutional monoallelic methylation, our analysis also identified mosaic constitutional methylation of the BRCA1 promoter in a male patient diagnosed with CRC at age 37 and with no family history of cancer." (PMID 41194282, 2025). "We observed that AND-1-binding by these cancer-related FANCJ mutants is severely compromised, while the DNA helicase activity and the interaction with other known protein binding partners (BRCA1, BLM and MLH1; see Fig. EV4A) is not altered, as compared to the wild-type protein." (PMID 38177925, 2024). "Recent studies indicate that regardless of BRCA1/2 status, inhibiting BRD4 with BETi decreases the expression of the DNA repair factor CtIP, inducing HR defects and enhancing DNA damage induced by PARP inhibitors in cancer cells." (PMID 39156700, 2024). "The uptake rates of surgical prevention could be lower in carriers of BRCA1/BRCA2 PVs identified from population-based testing, particularly in the absence of cancer within the family." (PMID 39264630, 2024). "Experimental evidence suggests exogenous aldehyde reduces levels of BRCA2, not BRCA1, and the low levels of BRCA2 could induce genome instability and cancer." (PMID 36345163, 2023). "Although we did not compare the findings of mammography between BRCA1 and BRCA2 patients, the higher rate of echogenic foci in BRCA2 cancers might suggest the importance of mammography in BRCA2 patients." (PMID 36905492, 2023). "Exon 7 deletion in BRCA1 was identified in six patients and was not reported previously in cohorts from other countries, which indicated a novel or specific LGR type in Chinese cancer patients." (PMID 36147908, 2022). "Interestingly, almost one third of MBC patients, who were carriers of P/LPVs in BRCA1 or BRCA2, had no family history of other HBOC-related cancers in their first- and/or second-degree relatives." (PMID 33891299, 2021). "The positive predictive value (PPV) of the prostate biopsy—number of cancers found divided by the number of biopsies—when PSA was >3.0ng/ml was 48% in BRCA2 carriers, 33.3% in BRCA2 non-carriers, 37.5% in BRCA1 carriers and 23.3% in BRCA1 non-carriers." (PMID 34884434, 2021). "However, comparison with population controls detected an increased occurrence in childhood cancers in families with a BRCA2 PGV, but not BRCA1." (PMID 34680915, 2021). "The epigenetic signatures of ATM, BRCA1, PALB2, RAD51B, and XRCC3 have also been explored in MBC (32.4% with germline BRCA2 PV) in matched normal and gynecomastia tissue samples (obtained from patients without cancer or a family history of BC)." (PMID 34298749, 2021). "Given the pronounced sensitivity to CuET in tumor cell lines lacking the genome integrity caretaker proteins BRCA1 and BRCA2, here we investigated the impact of NPL4 targeting by CuET on DNA replication dynamics and DNA damage response pathways in human cancer cell models." (PMID 32085572, 2020). "Interestingly, estrogen stimulation of breast cancer cells that do not express BRCA1 and, as a result, suffer from high intracellular ROS levels rescues NRF2 transcription, enhancing the survival of these cancer cells." (PMID 32060354, 2020).
cancer (continued). "Family history of MBC and additional primary cancer diagnoses were also not predictive of positive results in this cohort, consistent with current NCCN BRCA1/2 testing guidelines which recommend testing for MBC patients regardless of age at diagnosis or other clinical history." (PMID 28008555, 2017). "Notably, the immunoblot analysis of p-RPA in normal human controls (NHA-DRB, BJ) and the four non-GBM cancer cell lines (OVCAR5, Cal51, PC3 and HELA) confirmed elevated p-RPA levels after BRCA1 knockdown." (PMID 27845331, 2016). "However, it seems that in such cells, nuclear import of BRCA1/BARD1 is impaired rather than nuclear export of BARD1, thereby explaining its cytoplasmic accumulation and thus cancer development." (PMID 26402707, 2015). "However, no such influence is seen for BRCA1 or BRCA2 cases, which often have a much stronger family background of cancer." (PMID 15642173, 2005). "Numerous studies have shown that HDACi treatment across various cancer cell lines also results in the transcriptional downregulation of genes involved in homologous recombination and nonhomologous end-joining (Ku70, Ku86, DNA-PKcs, RAD51, BRCA1, and BRCA2), which are critical for DSB repair." (PMID 37991020, 2023). "Indeed, there are many papers that describe the detection of positive selection signals in BRCA1 and BRCA2 despite the fact that selective pressures on human cancer genes throughout mammalian evolution might not be directly associated with cancer." (PMID 38275383, 2023). "From the genes evaluated here, BRCA1, BRCA2, and PALB2 are part of the ACMG Secondary Findings v3.0 list and laboratories are now recommended to report GPV in these genes even in individuals without a personal or family history of cancer when next generation sequencing is performed." (PMID 35805029, 2022). "Of note, when analyzing non-HBOC core tumors, a significantly higher proportion of hepatic cancer was found in relatives of BRCA1/2 PV/LPV carriers than in non-carriers, suggesting that hepatic cancer could be a recurrent phenotype in the cancer spectrum of HBOC families." (PMID 36329109, 2022). "However, owing to the low expression of Parkin in cancer cells, we could not conclusively determine whether the knockdown of endogenous Parkin attenuates CCCP-induced BRCA1 degradation in MCF7 and A549 cells (data not shown)." (PMID 33888730, 2021). "Recent reports prove that the full length BRCA1 protein (but not C terminal mutant) via its BRCT domains interacts with and inhibits the protein super family ERM, which are located at the plasma membrane, resulting in the inhibition of the motility of cancer cells." (PMID 30224826, 2018). "Although there are no clinically meaningful prognostic or predictive cancer biomarkers available, a series of potential biomarkers have been identified, for example, in the blood (VEGF), on the cell surface (epithelial growth factor receptor 1 (EGFR)), and in the cell nucleus (BRCA1, BRCA2)." (PMID 29138528, 2017).
tumor (3,556 papers, 1995 to 2026). "A BRCA1 mutation was identified on tumor sequencing and was subsequently confirmed as a germline pathogenic variant." (PMID 42253309, 2026). "With the recent rise in CRISPR/Cas9-mediated genome-wide synthetic lethality screens, many new synthetic lethal targets have been identified for diseases with underlying genetic causes such as tumours with BRCA1 mutations." (PMID 42212547, 2026). "Olaparib is recommended for patients with germline or somatic tumor mutations in BRCA1/2, whereas niraparib is recommended for patients with recurrent HGSC of any genetic status." (PMID 41520277, 2026). "Although PARPis exploit SL in BRCA‐defective tumours, only about half of patients with BRCA1/2 mutations derive objective benefit." (PMID 41537447, 2026). "BRCA1-mutated tumors appeared more beneficial in HIPEC indicated that platinum-responsive tumor microenvironment is a critical modifier of HIPEC effect, which is consistent with previous clinical trials." (PMID 41416893, 2026). "Overall, our study reveals BRCA1 deficiency impedes tumor cell intrinsic innate immune response, inducing intrinsic resistance to PARP inhibitors that can be overcome when poly(I: C) is combined." (PMID 41520145, 2026). "Circulating tumor DNA (ctDNA) is the most clinically advanced analyte, supporting detection of actionable alterations such as BRCA1/2 and ATM mutations, guiding targeted therapies, and enabling real-time monitoring of treatment response and resistance." (PMID 42122162, 2026). "Tumours harbouring BRCA1/2 mutations are highly sensitive to PARPis, and BRCA1/2 deficiency has become one of the most robust and clinically validated predictive biomarkers for SL to date." (PMID 41537447, 2026). "Together, these findings show that loss of MDC1 counteracts the efficacy of PARPi in BRCA1/2-deficient tumor cells both in vitro and in vivo." (PMID 41408464, 2026). "Research has established that Breast Cancer Type 1 Susceptibility Protein (BRCA1) functions as a tumor suppressor, which is involved in the differentiation of mammary epithelial cells." (PMID 41463377, 2025). "Tumorigenesis is a multi-step process that includes an accumulation of gene mutations, and BRCA1 mutation alone is insufficient to initiate tumor development." (PMID 41154374, 2025). "The breast cancer susceptibility gene 1 (BRCA1, NM_007294.4) contains 23 exons and comprises 5592 nucleotides, encoding an 1863-amino-acid protein involved in numerous tumour suppressive functions, notably, DNA damage repair by homologous recombination." (PMID 41440233, 2025). "Patient tumors harboring DDR mutations, including 1100delC CHEK2 mutants and/or BRCA1/2 deleterious variants, showed higher percentages of tumor shrinkage (ORR = 86%) and longer overall survival (PFS = 30 months)." (PMID 40492861, 2025). "A study by Brodie and Deng demonstrated that BRCA1-deficient mice showed a loss of heterozygosity in some tumor suppressor genes and an amplification of genomic regions containing oncogenes." (PMID 40136510, 2025). "HGSOC is an excellent tumor model of HRD because a majority of cases exhibit mutations or hypermethylation in BRCA1/2 or other important HRR genes." (PMID 40830526, 2025). "Defects in HR repair can increase radiosensitivity, as demonstrated in tumours containing BRCA1/2 mutations, which displayed improved tumour control after radiotherapy due to an inability to repair SABR-induced double-stranded breaks." (PMID 41226343, 2025). "Regarding group B comprising cases with inactivating alterations in HRR associated genes other than BRCA1/2, we observed a wide variety of alterations affecting all investigated tumor entities." (PMID 40278800, 2025).
tumor (continued). "Model 1006 was selected as a prototypical homologous recombination–deficient tumor with both germline and somatic BRCA1 copy-number loss." (PMID 39514406, 2025). "Whilst BRCA1/2 mutations are a well-established biomarker of sensitivity to PARPi such as olaparib emerging evidence also supports its use in tumours with HRD resulting from somatic copy number losses." (PMID 41351070, 2025). "This meta-analysis further confirmed that BRCA1 mutations are associated with more aggressive tumor characteristics, including higher nuclear grade and larger tumor burden." (PMID 41249701, 2025). "The only significant clinical differences observed were in age; patients with BRCA1/2 mutations in the tumor tissue were younger compared to BRCA1/2 wt patients (p = 0.001)." (PMID 40427127, 2025). "In particular, the detection of tumour pathogenic variants in BRCA1/2 should trigger the referral of the patient for GC and germline testing if resources are available (Statement No. 13)." (PMID 40626014, 2025). "One hundred one cases with mutations in 20 HRR associated genes besides BRCA1/2 had been selected, affecting all investigated tumor entities (Group B)." (PMID 40278800, 2025). "Tumours arising in BRCA1-mutation carriers are overwhelmingly basal-like, whereas those in BRCA2-mutation carriers are predominantly luminal." (PMID 41463377, 2025). "In tumor cells with BRCA1/2 loss, the HRR pathway is deficient (HR deficiency (HRD)), leading to an accumulation of unrepaired DSBs." (PMID 39985088, 2025). "In MTP12 vs WTP12, there were 188 pathways enriched with significance, including positive regulation of ERK1 and ERK2, PI3K/AKT pathways and MAPK pathways, suggesting the activation of more tumor promoting factors in MTP12 due to Brca1 deficiency." (PMID 40157910, 2025). "Given their pivotal role in DNA repair, BRCA1/2 mutations can render tumor cells more susceptible to DNA-damaging agents like exatecan and other TOP1 inhibitors." (PMID 41077566, 2025). "BRCA1 is a commonly occurring tumor suppressor gene that encodes a nuclear protein with a molecular weight of 220 kDa." (PMID 39997609, 2025). "Olaparib inhibits polyADP ribose polymerase (PARP), blocking repair and enhancing cell death in BRCA1- or BRCA2-deficient tumours." (PMID 41020877, 2025). "It demonstrates that BRCA2-associated HGSOCs have a higher rate of complete tumor cell elimination upon NACT when compared to BRCA1-mutated tumors." (PMID 40547808, 2025). "In 2005, researchers reported the synthetic lethal relationship between PARP inhibitors and BRCA1/2 mutations, offering a novel therapeutic approach for patients with BRCA1/2‐mutant tumours." (PMID 40859871, 2025). "PALB2, just like BRCA1/2, acts as a tumor suppressor, and pathogenic germline mutations increase the risk of breast, ovarian, and pancreatic cancers, underscoring its shared involvement in DNA repair." (PMID 41374970, 2025). "PARP inhibitors (PARPi) mostly act through PARP1 trapping, which stalls replication forks and causes synthetic lethality in HR-deficient tumours, such as BRCA1/2-defective cancers." (PMID 41188872, 2025). "All models demonstrated good performance in identifying BRCA1/2‐deficient tumours; and as seen in the training dataset, models that integrated several data types produced better performance, proving that augmenting information improves model prediction." (PMID 40260608, 2025). "HRD-positive tumours, including those harbouring BRCA1/2 mutations, generally demonstrate better responses to platinum compared to tumours with wild-type BRCA1/2 genes." (PMID 40141188, 2025). "This strategy proves especially effective in tumours harbouring BRCA1 or BRCA2 mutations, leveraging their intrinsic vulnerabilities attributed to the mechanism of synthetic lethality." (PMID 40256842, 2025).